BRWD3 (bromodomain and WD repeat domain containing 3)
Description:
Required for regulation of cell morphology and cytoskeletal organization.
Synonyms: BRODL; MRX93; FLJ38568; DCAF20; XLID93
Tractability: PROTAC: ubiquitination databases record sites on it; its protein half-life has been measured.
Target class: Epigenetic regulator; Bromodomain; Reader
Gene: Protein-coding gene on chromosome X (80,669,503 to 80,809,877, reverse strand). Ensembl gene ENSG00000165288.
Subcellular location (Human Protein Atlas): Nucleoplasm; Cytosol
Gene Ontology:
Biological process: cytoskeleton organization; regulation of cell shape; regulation of transcription by RNA polymerase II
Cellular component: nucleus
Gene-disease validity (ClinGen):
ClinGen rates the evidence that BRWD3 causes each of these diseases.
X-linked syndromic intellectual disability (X-linked): Definitive. A syndromic intellectual disability with an X-linked mode of inheritance.
Homologues: Orthologues: chimpanzee BRWD3 (99% identical), macaque BRWD3 (99% identical), dog BRWD3 (95% identical), mouse Brwd3 (95% identical), rat Brwd3 (95% identical), pig BRWD3 (92% identical), guinea pig BRWD3 (90% identical), rabbit BRWD3 (78% identical), tropical clawed frog brwd3 (70% identical), zebrafish brwd3 (55% identical), Drosophila melanogaster BRWD3 (38% identical). Paralogues in human: PHIP (55% identical), BRWD1 (54% identical).
Diseases named in the same sentence as BRWD3 in open-access papers:
BRWD3 is named in the same sentence as 28 diseases in open-access papers, as found by Europe PMC text mining. Sharing a sentence is not in itself a finding about the gene and the disease. The quoted sentences say what the papers report.
Intellectual disability (8 papers, 2011 to 2024). "Further analysis demonstrated that previously reported destructive mutations of BRWD3 were associated with intellectual disability, while the missense variants in WD40 repeat domains and bromodomains were associated with epilepsy." (PMID 36514184, 2023). "Further analysis demonstrated that all previously reported destructive variants of BRWD3 caused intellectual disability, while missense variants located in WD40 repeat domains and bromodomains of BRWD3 were associated with epilepsy." (PMID 36514184, 2023). "Two causes of intellectual disability are 15q13.3 deletion syndrome and BRWD3 X-linked intellectual disability." (PMID 36548204, 2022). "BRWD3 is documented to be associated with the onset of mental retardation, X-linked 93, and the identified variants were truncated mutation or partial deletions." (PMID 31178897, 2019). "Loss of function mutations affecting BRWD3 are associated with a phenotype including mild to moderate intellectual disability, macrocephaly, dysmorphic facial features, skeletal signs and behavioral disturbance." (PMID 26323392, 2015). "Two genes P2PRY10 and BRWD3 of 11 genes on the cytoband Xq21.1, found to show copy number variation in mosaic form, could also have a possible role in the causation of mental retardation." (PMID 21968244, 2011). "The BRWD3 gene (MIM 300553), located at Xq21.1, is associated with X-linked mental retardation and macrocephaly, while TCF20 (MIM *603107) variants with intellectual disability and postnatal overgrowth." (PMID 36833222, 2023). "In conclusion, this study identified three novel variants of BRWD3 (including two recurrent missense variants) in the patients with partial epilepsy with favorable outcome and without intellectual disability." (PMID 36514184, 2023). "BRWD3 gene is potentially associated with X‐linked partial epilepsy without intellectual disability." (PMID 36514184, 2023).
breast carcinoma (3 papers, 2014 to 2021). "Suh EJ, Kabir MH, Kang UB, Lee JW, Yu J, Noh DY, Lee C: Comparative profiling of plasma proteome from breast cancer patients reveals thrombospondin-1 and BRWD3 as serological biomarkers." (PMID 27454254, 2016). "Another study using plasma showed that thrombospondin-1 (THBS1) and bromodomain and WD repeat-containing protein 3 (BRWD3) were overexpressed in breast cancer using mTRAQ and Western blot." (PMID 24550697, 2014). "While the function of BRWD3 in relation to cancer development is unknown at this time, BRWD3 was shown to be up-regulated in breast cancer patient’s plasma and has potential for use as a serological biomarker." (PMID 34298819, 2021). "BRWD3 is a known serological biomarker in breast cancer patients." (PMID 27454254, 2016).
Macrocephaly (3 papers, 2011 to 2025). Occipitofrontal (head) circumference greater than 97th centile compared to appropriate, age matched, sex-matched normal standards. "Mutations in BRWD3 cause mental retardation X-linked type 93, which is also referred to as mental retardation X-linked with macrocephaly." (PMID 21968244, 2011).
X-linked intellectual disability (3 papers, 2015 to 2023). An X-linked intellectual deficiency in which not enough information is known, reported or published to indicate whether a gene causes non-syndromic or syndromic presentations. "Multiple human genetic studies have demonstrated that human BRWD3 and KDM5C mutations underlie X-linked intellectual disability." (PMID 37034668, 2023).
developmental delay (2 papers, 2023 to 2026). "In animal model, hemizygous deficiency of BRWD3 mice exhibited microcephaly and developmental delay." (PMID 36514184, 2023).
microcephaly (2 papers, 2022 to 2023). A congenital or acquired developmental disorder in which the circumference of the head is smaller than normal for the person's age and sex. "The syndromes or intellectual developmental disorders caused by variants in DIAPH1, AFF2, BCORL1 and BRWD3 are occasionally with abnormalities of cranium, such as microcephaly or macrocephaly tall forehead." (PMID 36118902, 2022). "Hemizygous deficiency of BRWD3 mice exhibited embryonic growth retardation and microcephaly." (PMID 36514184, 2023). "Knockout of BRWD3 in mice exhibited short tail buds, microcephaly and, in some cases, embryonic growth retardation." (PMID 36514184, 2023).
epilepsy (1 paper, 2023). A brain disorder characterized by episodes of abnormally increased neuronal discharge resulting in transient episodes of sensory or motor neurological dysfunction, or psychic dysfunction. "Further studies on the pathological consequences/neurological dysfunction are required to elucidate the essential link between the BRWD3 variants and epilepsy." (PMID 36514184, 2023). "Taking together the evidence that BRWD3 is expressed in brain and essential for normal neurodevelopment, BRWD3 is suggested to be potentially a candidate pathogenic gene of epilepsy." (PMID 36514184, 2023). "However, the association between BRWD3 mutations and epilepsy remains unknown." (PMID 36514184, 2023). "Clinically, all destructive mutations of BRWD3 caused MRX93; while missense mutations, intronic variants close to splice sites, and small gross duplications were potentially associated with epilepsy with infancy or childhood onset, suggesting a genotype–phenotype correlation." (PMID 36514184, 2023). "This study reports three novel variants of BRWD3 in five unrelated cases with partial epilepsy and without mental retardation and demonstrates that the BRWD3 gene is potentially a candidate pathogenic gene of epilepsy." (PMID 36514184, 2023). "However, the link between BRWD3 and epilepsy remains unknown." (PMID 36514184, 2023).
partial epilepsy (1 paper, 2023). "Taking together the evidence that BRWD3 gene is expressed in brain and associated with neurodevelopment, the BRWD3 gene is suggested to be potentially a candidate pathogenic gene of partial epilepsy." (PMID 36514184, 2023). "Among the 320 patients with unexplained partial epilepsy, three BRWD3 variants were identified in five unrelated cases, including two recurrent missense variants (c.836C>T/p.Thr279Ile and c.4234A>C/p.Ile1412Leu) and one intronic variant close to splice site (c.2475 + 6A>G)." (PMID 36514184, 2023). "In this study, three BRWD3 variants were identified in five unrelated cases with partial epilepsy." (PMID 36514184, 2023). "In the present study, we identified BRWD3 variants in five unrelated cases with partial epilepsy." (PMID 36514184, 2023).
cancer (9 papers, 2008 to 2023). A tumor composed of atypical neoplastic, often pleomorphic cells that invade other tissues. "Further, higher BRWD3 mutation rates have been found in cancers and linked to a decrease in overall survival." (PMID 37034668, 2023). "Mutations in the BRWD3 family of genes were recently identified as the cause of a neurodevelopmental disorder and altered BRWD3 expression has been found in various cancers." (PMID 37034668, 2023). "Besides that, other CSV interactions also can be a predictive biomarker in other cancers, such as BRWD3 and PSMB8 in LUAD (P = 8E−04, log-rank test), as well as CNTN2 and HDAC11 (P = 0.01, log-rank test) in LUAD." (PMID 36180906, 2022). "While little is known about the functional involvement of BRWD3 and PECR in human cancers, an enrichment of FOS as part of a heterodimer with JUN has previously been linked to anchorage-independent cell growth in our HPV-transformed cell lines as well as HeLa." (PMID 32188026, 2020). "By contrast, in human PDA tumors, containing cancer and stromal cell types, nearly all HDACs (except SIRT4) and BETs (except BRDT, BRWD3, and CECR2) were highly expressed." (PMID 33244070, 2020).
neurodevelopmental disorder (3 papers, 2013 to 2023). A behavioral and cognitive disorder with onset during the developmental period that involves impaired or aberrant development of intellectual, motor, or social functions. "Here, we use the roles of BRD2 and BRWD3 in neurodevelopmental disorders as examples." (PMID 23425632, 2013).
tumor (2 papers, 2008 to 2021). "The list of genes with reduced expression in DA, as compared with increased expression in DA.F344(Cia5d) congenics, included seven genes that are involved in tumor suppression-like activity and cell cycle check-points, such as Aph1a, Brwd3, Gadd45b, Gmfg, Lox, and Plekhg2." (PMID 18706093, 2008).
hematological malignancies (1 paper, 2025). "Though the function of BRWD3 in hematological malignancies has not been revealed yet, BRWD1 is considered as a master orchestrator of late B-cell development." (PMID 40282457, 2025).
BRWD3 also shares sentences with these, for which no sentence is quoted: Angelman syndrome (1 paper); central obesity (1); cleft palate (1); colorectal cancer (1); hypogonadism (1); Infertility (1); intellectual disability syndromes (1); intellectual impairment (1); Kabuki syndrome (1); language delay (1); mental retardation X-linked type 93 (1); Pes cavus (1); Rett syndrome (1); Seizure (1); Tremor (1); X-linked deafness (1).